MLKL (mixed lineage kinase domain like pseudokinase)
Diseases named in the same sentence as MLKL in open-access papers (continued):
Sharing a sentence is not in itself a finding about the gene and the disease.
tumor (continued). "Further assessment demonstrated that the expression of necroptosis-related genes, including FADD, MLKL, TLR2, PGAM, HMGB1, CXCL 1, TRAF2, and EZH2, was elevated in tumor tissue, while FAS, RIPK1, RIPK3, TLR3, TNFRSF, ALDH2, and NDRG2 were upregulated in normal intestinal tissues." (PMID 40959081, 2025). "In vivo, implantation of RIPK1−/− or MLKL−/− U251 cells into nude mice failed to form subcutaneous tumors, in sharp contrast to robust tumor growth observed for the corresponding wild-type controls." (PMID 41429922, 2025). "For instance, MLKL-mediated necroptosis releases CXCL5, which recruits MDSCs and suppresses T-cell activity while elevated RIPK3 expression drives an immunosuppressive microenvironment through CXCL1, thereby accelerating tumor progression." (PMID 41267084, 2025). "Regardless of the expression of RIPK3 and MLKL, tumor cells showed necrotic morphological characteristics when treated with NB under US irradiation, suggesting that the occurrence of cell necroptosis was independent of RIPK3/MLKL." (PMID 37984863, 2024). "We demonstrated for the first time that the tumor tissues and cell lines of TNBC were characterized by the high expression of MLKL and the use of CNLs as necroptosis-inducing reagents was therapeutically effective in TNBC cells highly expressing MLKL." (PMID 38474369, 2024). "We found that blocking tumor necroptosis by MLKL deletion in both MMTV-PyMT mice and MVT-1 tumors resulted in the dramatic reduction of tumor metastasis to the lungs and the increase in the anti-tumor activity of both tumor-infiltrating and peripheral blood T cells." (PMID 36703228, 2023). "It is tempting to speculate that MLKL-dependent pore formation may facilitate release of mtDNA to stimulate cGAS/STING, which in turn induces the first wave of IFN within the necroptotic tumor cells." (PMID 38196632, 2023). "Previous studies indicated that pore forming proteins (PFPs) such as BAX/BAK, mixed lineage kinase domain-like (MLKL) and gasdermins (GSDs) play a significant role in addressing tumor resistance via non-apoptotic cell death." (PMID 36936526, 2023). "Our evidence suggests that MLKL acts as a cancer promoter in LUAD, and it may mediate the initiation of inflammation in the tumor microenvironment, thereby promoting tumor metastasis and growth." (PMID 37864090, 2023). "Interestingly, we found that the expression of MLKL and APP in BUC was positively correlated with immune cell infiltration, but negatively correlated with tumor stemness." (PMID 37000317, 2023). "To date, the functional role of the necroptosis executor MLKL in tumor development has not been intensively studied." (PMID 35422482, 2022). "Regarding GHPPA tumors as a matter of tumor size, it was observed that 81.81% of invasive macro adenoma GHPPA were negative for MLKL expression; while 66.66% of invasive GHPPA with micro adenoma were positive for MLKL protein." (PMID 34983494, 2022). "Meanwhile, the genetic knockout of MLKL, the executive protein in the necroptosis cascade, did not prevent a reduction in tumor sphere formation, suggesting that ASIC1a induced an alternative cell death pathway." (PMID 35961983, 2022). "Furthermore, some studies have reported that MFN2 exerts anti-tumor effects; in our study, we also confirmed that MFN2 promoted RIP3/MLKL complex-induced necroptosis in the Huh7 cell line." (PMID 35154486, 2022). "However, that of MLKL in both hilar and intrahepatic CCA was much lower than that of RIPK3 in adjacent tumor tissues, in which 88.7% of the patients had a median H-score of 22.03, which was subsequently interpreted as negative." (PMID 34083572, 2021). "The status of MLKL immunoreactivity was significantly higher in both hilar (n = 68) (p-value = 1.1394E−24) and intrahepatic CCA tissues (n = 21) (p-value = 7.8992E−10) than adjacent tumor tissues." (PMID 34083572, 2021).
tumor (continued). "The present study revealed both RIPK1/RIPK3/MLKL and RIPK1/caspase-8/caspase-3 pathways were inhibited in TNBC tumor samples and AQP1-expressing cell lines, which is in agreement with our presumption that both RIPK1-dependent necroptosis and apoptosis are attenuated by AQP1." (PMID 33980862, 2021). "We found that tumor necrosis and MLKL phosphorylation were not affected by the administration of Nec-1." (PMID 33976222, 2021). "P-MLKL can be detected in some tumor tissues, whereas no p-MLKL expression was detected in 40 stained TAE sections." (PMID 32444644, 2020). "Transient events such as phosphorylation of RIPK3 and MLKL are not easily detectable in the context of human or murine tumor models." (PMID 32231206, 2020). "The mRNA expression of RIPK1, RIPK3, and MLKL in tumor tissues was significantly correlated with each other (r = 0.46, P <0.001, between RIPK1 and RIPK3; r = 0.35, P <0.001, between RIPK1 and MLKL; r = 0.43, P <0.001, between RIPK3 and MLKL)." (PMID 32742497, 2020). "Therefore, we examined the total MLKL and p-MLKL levels in the PC3, 22RV1 and mouse tumor tissues samples, respectively." (PMID 32984054, 2020). "To complement experiments involving systemic Nec-1s administration, we vaccinated with dying tumor cells lacking MLKL and show that immunogenic effects of Mito+oHSV-1 treated dying cells are lost." (PMID 33149194, 2020). "The expression of RIP3 and MLKL were elevated in resibufogenin treated shControl tumor tissues but not in RIP3-knockdown tumors." (PMID 30029665, 2018). "Likewise, only MLKL-mRNA treatment resulted in significant numbers of interferon-γ (IFN-γ) producing OVA-peptide-specific CD4+ and CD8+ T cells in the tumor draining lymph node." (PMID 30143632, 2018). "In addition, tumor cells evade necroptosis, a RIPK1/RIPK3/MLKL-dependent death pathway, through downregulation of RIPK3 or MLKL expression, or by exploiting molecular chaperones to suppress pathway activation, enabling escape from TNFα family cytokines or certain chemotherapy-induced cell death." (PMID 41229498, 2025). "Similarly, in breast cancer models, the absence of RIPK1, RIPK3, and MLKL results in slower tumor growth and heightened sensitivity to radiotherapy." (PMID 39949740, 2025). "To address the role of tumor cell necroptosis in cancer immunotherapy with ICI, we used CRISPR-mediated somatic mutagenesis to generate polyclonal tumor cell lines that lack critical components of the necroptotic cell death molecular machinery (RIPK3−/−, MLKL−/−)." (PMID 40345706, 2025). "Additionally, MLKL has been reported to possess a tumor-suppressive effect during intestinal oncogenesis in certain research, yet the genetic deletion of MLKL showed no influence on CRC advancement." (PMID 40959081, 2025). "Additionally, fibroblasts in the tumor microenvironment can drive immune responses through necroptosis-induced NF-κB signaling rather than MLKL-mediated DAMPs release." (PMID 40969770, 2025). "In addition, high NRGscore patients always had more mRNA levels of three necroptosis-driving genes (MLKL, RIPK1, and RIPK3), further validating that necroptosis could play a tumor-promoting role in HCC." (PMID 35875102, 2022). "However, unlike the elevated ROS, both MLKL protein-mediated necroptosis and the release of perforin did not occur at the early stage when tumor cells arrived at the liver." (PMID 36438480, 2022). "However, both carbon ion and X-ray treatment did not upregulate the phosphorylation level of MLKL in other tumor cells (HepG2 and Hep2 cells) at 48 hours." (PMID 33531997, 2021). "Thus, MLKL is a potential target for anti-tumor treatments but upregulation of MLKL is not a one-size-fits-all approach to cancer." (PMID 33754026, 2021).
tumor (continued). "The tumor-suppressing activity of necroptosis has been shown in many types of cancer in which the expression of RIPK3 or MLKL is silenced by methylation or altered by polymorphisms in coding genes, suggesting that cancer cells evading apoptosis may also escape from necroptosis." (PMID 33050394, 2020). "For instance, while multiple studies have indeed found that, whole tumor-biopsy level, high expression of RIPK3 or even sometimes MLKL may predict prolonged cancer patient survival, yet high expression of RIPK1 or MLKL has also been documented to predict worse prognosis for some cancer patients." (PMID 32752206, 2020). "A preclinical study showed that necroptosis-associated tumour repopulation after radiotherapy depended on activation of the RIP1/RIP3/MLKL/JNK/IL-8 pathway and this novel pathway could be a promising target for blocking tumour repopulation to enhance the efficacy of colorectal cancer radiotherapy." (PMID 33008040, 2020). "Interestingly, tumorigenicity experiments showed that there was no tumor formation in nude mice after knockdown of MLKL, in contrast to vector-transduced HT29 cells." (PMID 31706322, 2019). "Therefore, future studies incorporating expression analyses of key markers such as LC3B, p62, and p-MLKL may help elucidate TIG3′s potential role in regulating these non-canonical cell death pathways, ultimately enhancing our understanding of its anti-tumor mechanisms." (PMID 40722819, 2025). "Alternative approaches to enhance necroptosis signaling in tumor cells may include manipulation of ADAR1, which was shown to mask ZBP1-driven necroptosis, or therapeutic induction of IFN-I signaling in the TME as MLKL and other critical components are IFN-stimulated genes." (PMID 40345706, 2025). "Further studies focused in investigating the role of necroptosis in gliomagenesis and tumor progression will elucidate whether MLKL and RIPK3 are not only relevant LGG prognostic biomarkers but also potential targets for therapeutic intervention, as they constitute the core machinery of necroptosis." (PMID 37651429, 2023). "Moreover, upon the inhibition of necroptotic cell death through addition of Nec-1 or knockdown of MLKL, the conditioned medium failed to affect the migration and invasion of treated cells, indicating that the tumor-promoting effect was cell death dependent rather than drug dependent." (PMID 32444644, 2020). "However, intratumor treatment of primary tumors with MLKL-mRNA induced a robust protection against tumor rechallenge with 40% of the B16 inoculated mice being tumor free by day 86 and all of the CT26 inoculated mice remaining tumor free up to day 60 of the experiment." (PMID 30143632, 2018). "Necroptosis, unlike apoptosis, results in plasma membrane rupture via mixed lineage kinase domain like pseudokinase (MLKL)-mediated pore formation and, hence, is an inflammatory type of cell death with reported anti-tumor activity." (PMID 41413044, 2025). "In several tumor cells, RIPK3 is often silenced by methylation near the transcriptional initiation site, which inhibits the activation of MLKL and fails to mediate necroptosis, consequently promoting tumor development." (PMID 38684668, 2024). "In non-invasive GHPPA tumors regarding tumor size the difference was not remarkable and 55.55 and 58.82% of non-invasive micro- and macro- GHPPA tumors negatively expressed MLKL protein." (PMID 34983494, 2022). "Consistent with our early finding that RIPK1 is not required for tumor necroptosis during tumor development, we found that RIPK1 is not required for GD-induced MLKL phosphorylation." (PMID 33976222, 2021). "To further demonstrate this, we used the MLKL inhibitor Necrosulfonamide (NSA) to inhibit necroptosis and observed that overexpressed RIP3 no longer inhibited the tumor cells’ ability to proliferate." (PMID 32984054, 2020).
tumor (continued). "The MLKL-mRNA-based therapy described here resulted in the clear induction of tumor antigen-specific CD4+ and CD8+ T cell responses without a necessity for tumor sequencing, epitope prediction, and production of a personalized vaccine vector." (PMID 30143632, 2018). "Cells from the 148I tumor also lacked any detectable RIPK3 expression and bore only low levels of MLKL." (PMID 27129149, 2016). "Interestingly, studies have shown that the release of bioactive IL-1β within tumours does not depend on the activation of inflammasomes, caspase-8, the pore-forming protein GSDMD, or mixed lineage kinase domain-like protein (MLKL)." (PMID 40234383, 2025). "Therefore, in the context of inflammatory and neoplastic diseases, RIPK3 and MLKL do not necessarily represent the onset of necroptosis, and their roles will need to be assessed in each disease model individually." (PMID 36828808, 2023). "Although CT26 tumor cells do not express RIPK318, the therapeutic effect of MLKL-mRNA treatment resulted in a very pronounced antitumor effect, increasing the median survival time to >60 days and 60% of the treated mice even remained tumor free up to 80 days after CT26 inoculation." (PMID 30143632, 2018). "Besides, the knockdown of A20 could hardly induce the up-regulation of cleaved-Caspase 3, phosphor-MLKL or cleaved-GSDME in isolated xenograft tumors, indicating that cell death might not be involved in the effect of A20 on tumor progression both in vivo and in vitro." (PMID 32968045, 2020).
cancer (148 papers, 2015 to 2026). A tumor composed of atypical neoplastic, often pleomorphic cells that invade other tissues. "Some of them connect MLKL with processes other than necroptosis, for example, endosomal trafficking and extracellular vesicle formation, 38 which we recently linked to cancer immunosurveillance." (PMID 40345706, 2025). "This analysis showed that almost all of the tested variants of DS significantly increased the level of phospho-MLKL in both cancer lines, with the maximum effect being detected after 3.5 h of exposure." (PMID 39062543, 2024). "Decreased MLKL expression is associated with a poor prognosis for patients with gastric, ovarian and colon cancer." (PMID 38213773, 2024). "In the murine cancer-associated fibroblasts mCAF-3, all three viruses show a similar induction of p-MLKL expression (between 2.5 and 2.7), although it seems that mCAF-3 cells are somewhat less sensitive to reovirus T3DK compared to the other reoviruses." (PMID 36768641, 2023). "In the murine cancer-associated fibroblast cells, mCAF-3, all three reoviruses increased p-MLKL, although to lower levels than seen in the L929 cells." (PMID 36768641, 2023). "In several human diseases, including cancer, necroptosis causes caspase-independent programmed cell death mediated by the MLKL signaling cascade." (PMID 36874011, 2023). "The reduced expression of RIPK3 and MLKL is associated with worse prognosis and poor survival in these cancers." (PMID 39872161, 2022). "There are still many unsolved questions: does MLKL cleavage occur in other RIPK3-deficient cancer cells and is the C-terminal cleavage ubiquitinated and degraded by proteasome after cleavage." (PMID 35965541, 2022). "Odds ratios or hazards ratios (HRs) with corresponding 95% confidence intervals (CIs) were pooled to estimate the association between MLKL expression and clinicopathological characteristics or survival of cancer patients." (PMID 30005626, 2018). "The results indicated that decreased expression level of MLKL was significantly associated with poor EFS of cancer patients." (PMID 30005626, 2018). "Through systematic analysis, our results demonstrated that decreased expression level of MLKL was significantly associated with poor OS in cancer patients." (PMID 30005626, 2018). "We analyzed the association between MLKL expression levels with clinicopathological characteristics of cancers patients." (PMID 30005626, 2018). "The consequence displayed that decreased expression level of MLKL was significantly associated with poor EFS in cancer patients (HR = 0.45, 95%CI: 0.23–0.87, p = 0.017)." (PMID 30005626, 2018). "The pooled HR for OS was 0.26 (95%CI: 0.17–0.40, p < 0.001), which indicated that decreased expression level of MLKL was significantly associated with poor OS in cancer patients." (PMID 30005626, 2018). "Consequently, loss/downregulation of RIP3 and MLKL expression are seen in a variety of cancer types and cancer cell lines which correlated with poor survival rate." (PMID 38926796, 2024). "Furthermore, the low expression of MLKL appears to be associated with a poor patient prognosis in certain cancers, making it a potential novel potential prognostic biomarker for these cancers." (PMID 38239395, 2023). "From these findings, an alternative necroptotic pathway may be inferred in RIPK3-deficient cancer cells, for example in MM cells, where necroptosis may be executed by N-terminal cleavage of MLKL when caspases are activated." (PMID 35965541, 2022). "A similar study also found that a higher level of phosphorylated MLKL was linked with a worse prognosis and shorter survival in human patients with esophageal and colorectal cancer, suggesting that necroptotic genes play a key role in cancer progression." (PMID 36361505, 2022).